BCL3 (BCL3 transcription coactivator)
Diseases named in the same sentence as BCL3 in open-access papers (continued):
Sharing a sentence is not in itself a finding about the gene and the disease.
chronic lymphocytic leukemia (20 papers, 2009 to 2026). "Bcl-3 mutations in lymphocytes give rise to overexpression of IκB protein and uncontrolled cell proliferation, which lead to B-cell chronic lymphocytic leukemia." (PMID 38195591, 2024). "Although the implication of BCL3 has been disclosed in human chronic lymphocytic leukemia as well as other solid tumors, the diagnostic and prognostic of BCL3 expression in acute myeloid leukemia (AML) remains largely unclear." (PMID 30357752, 2019). "Moreover, Bcl-3 mutations in lymphocytes give rise to overexpression of IκB protein and uncontrolled cell proliferation, which lead to B-cell chronic lymphocytic leukemia." (PMID 35355979, 2022). "Bcl3 (B cell lymphoma factor 3) was originally identified as a gene involved in genomic translocations in cases of B cell chronic lymphocytic leukemia (B-CLL)." (PMID 36318581, 2022). "Investigations with regard to the correlation between LINC00176 and promoter region of CP turned out to be positive via B‐cell CLL/lymphoma 3 (BCL3) by means of dual‐luciferase reporter gene assay, ChIP and RIP assays." (PMID 31668012, 2020). "B-cell lymphoma 3 (BCL3) was first identified as a proto-oncogene in patients suffering from B-cell chronic lymphocytic leukemia." (PMID 29587428, 2018). "BCL3 is a proto-oncogene that belongs to the IκB family, and its aberrant expression was first reported in chronic B cell lymphocytic leukemia." (PMID 26219963, 2015). "Bcl-3 is an established oncogene in hematologic malignancies, such as B-cell chronic lymphocytic leukemias." (PMID 22195643, 2011). "BCL3 locus has been found to be translocated not only in B-cell chronic leukemias, but also in other hematological malignancies, such as small lymphocytic lymphomas, Burkitt-like lymphoma and diffuse large cell lymphoma." (PMID 22195643, 2011). "Interestingly, RNAi-mediated ablation of BCL3 (B-cell CLL/Lymphoma 3) expression in activated fibroblasts, leads to a strong decrease of ICAM-1 expression both in LIF-activated fibroblasts and in CAF (data not shown)." (PMID 27901489, 2017). "Bcl-3 overexpression is also associated with a number of cancers that do not harbor BCL3-associated translocations, including classical Hodgkin’s and peripheral T-cell lymphoma, chronic lymphocytic leukemia, adult T cell leukemia, and certain solid tumors." (PMID 27023613, 2016). "Given its identification as a proto-oncogene in chronic lymphocytic leukaemia and central role in regulating NF-κB signalling, it is perhaps not surprising that there have been an increasing number of studies in recent years investigating the role of BCL-3 in a variety of human solid cancers." (PMID 31930327, 2020). "Approximately 1% of chronic lymphocytic leukemia (CLL) cases harbor a translocation juxtaposing the immunoglobulin heavy chain (IGH) and B-cell lymphoma 3 (BCL3) loci." (PMID 42064384, 2026).
ovarian carcinoma (18 papers, 2011 to 2025). A malignant neoplasm originating from the surface ovarian epithelium. "It is important to note that the Catalog of Somatic Mutations in Cancer (COSMIC) has a very low number of BCL3 mutations (2 missense mutations, one in a lung cancer and a second in an ovarian cancer patient) among its large database." (PMID 22195643, 2011). "Recent studies have shown that IFNγ induces the expression of Bcl3, which then promotes the expression of PD-L1 and IL-8 in ovarian cancer cells, resulting in their increased proliferation and migration." (PMID 39123403, 2024). "An association between Bcl3, NF-κB pathway, and PDL1 expression has recently been reported in ovarian cancer cells." (PMID 38418707, 2024). "The induction of IL8 by BCL3 in ovarian cancer cells highlights one presumptive mechanism of BCL3-cytokine driven immune evasion in solid tumours via the recruitment of tumour-associated neutrophils." (PMID 38195591, 2024). "In this review, we summarize the recent findings on the IFNγ tumor-promoting functions and on the mechanisms by which IFNγ induces Bcl3, PD-L1 and IL-8 expression in cancer cells, with a special focus on ovarian cancer." (PMID 39123403, 2024). "In this review, we summarize the recent findings on how IFNγ affects the tumor microenvironment and promotes tumor progression, with a special focus on ovarian cancer and on Bcl3, PD-L1 and IL-8/CXCL8 signaling." (PMID 39123403, 2024). "In ovarian cancer cells, the tumor-promoting effects of IFNγ are mediated by increased expression of the proto-oncogene Bcl3, the immune checkpoint PD-L1 and the proinflammatory cytokine IL-8." (PMID 39123403, 2024). "The Bcl3 expression is increased in hematological malignancies and many types of solid tumors including ovarian cancer (OC)." (PMID 37151134, 2023). "We further looked at several p52 target genes expression in ovarian cancer A2780 cells upon Bcl3 overexpression using lentiviral transduction." (PMID 35990614, 2022). "The LINC00176/BCL3/CP axis facilitates the epithelial-mesenchymal transition (EMT) process in ovarian cancer." (PMID 34413268, 2021). "Our results demonstrate that restored LINC00176 initiates tumorigenesis in ovarian cancer by increasing CP expression via recruiting BCL3, the mechanism of which represented a potential and promising therapeutic target for the disease." (PMID 31668012, 2020). "Critically, the proto‐oncogene BCL3 has been detected to express highly in human ovarian cancer tissues where ovarian cancer cell survival, proliferation and migration are promoted, supporting our results with regard to the rescue properties of silencing BCL3." (PMID 31668012, 2020). "Recently, in ovarian cancer cells, a new regulation step was found, which involves miR-125b a microRNA that decreased Bcl-3 translation, inhibiting tumor formation in nude mice." (PMID 22195643, 2011). "Bcl3 mediates cell proliferation by inducing PD-L1 expression in ovarian cancer." (PMID 40427768, 2025). "In ovarian cancer (OC) cells, the tumor-promoting functions of IFNγ are mediated by IFNγ-induced expression of Bcl3, PD-L1 and IL-8/CXCL8, which have long been known to have critical cellular functions as a proto-oncogene, an immune checkpoint ligand and a chemoattractant, respectively." (PMID 39123403, 2024). "In addition, interferon (IFN) can promote the expression of BCl3 in ovarian cancer cells and increase the transcription level of the immune checkpoint molecule PD-L1." (PMID 38779358, 2024). "Future studies are warranted to determine whether Bcl3 may serve as a potential biomarker in ovarian cancer and whether Bcl3 inhibition might be used as an antimetastatic strategy in ovarian cancer and other solid tumors." (PMID 39123403, 2024). "Thus, the newly emerging functions of Bcl3 in ovarian cancer include the induction of OC cell proliferation, survival, migration and invasion and also angiogenesis and immune escape." (PMID 39123403, 2024).
ovarian carcinoma (continued). "Since Bcl3, PD-L1 and IL-8 promote tumorigenesis, combinatorial strategies targeting the IFNγ-induced Bcl3, PD-L1 and IL-8 expression in ovarian cancer may enhance the antitumor effects of cancer immunotherapies." (PMID 39123403, 2024). "Bcl3 upregulated PD-L1 expression in ovarian cancer cells mediated by IFN-γ." (PMID 38418707, 2024). "One such checkpoint protein, PDL-1, has recently been shown to be under the transcriptional control of BCL3 in ovarian cancer cells, suggesting that inhibition of BCL3 may promote immune responses in this cancer type." (PMID 38195591, 2024). "Previous studies have found that BCL3 is highly expressed in ovarian cancer tissues." (PMID 38779358, 2024). "The IFNγ‐induced Bcl3 promotes expression of interleukin‐8 (IL‐8) in ovarian cancer cells." (PMID 37151134, 2023). "Bcl3 has been shown to contribute to tumorigenesis in glioma and ovarian cancer." (PMID 35990614, 2022). "In addition, PPARγ can induce growth suppression of ovarian cancer by transcriptional upregulation of miR-125b and thereby inhibits proto-oncogene BCL3." (PMID 28881624, 2017). "Furthermore, ectopic expression of miR-125b in ovarian cancer cells induced cell cycle arrest and led to reduction in proliferation and clonal formation through the repression of a proto-oncogene, BCL3." (PMID 28881624, 2017). "In addition, miR-125b targets proto-oncogenic BCL3, which can suppress ovarian cancer cell growth, and overexpressed ARID3B in ovarian cancer is a target of miR-125a." (PMID 21541038, 2011). "Therefore, we proposed a hypothesis asserting that the LINC00176/BCL3/CP axis may play a novel role in the progression and development of ovarian cancer via confirmation by a series of in vitro and in vivo experiments." (PMID 31668012, 2020). "PD-L1 is known to inhibit tumour infiltrating lymphocytes; therefore, it is tempting to speculate that BCL-3 could play a similar role in protecting against tumour cell apoptosis via regulation of tumour infiltrating lymphocytes in both hepatocellular carcinoma and ovarian cancer." (PMID 31930327, 2020). "Delivery of si‐LINC00176, oe‐LINC00176, si‐BCL3 and si‐CP plasmids was conducted to explore the effects of LINC00176 on ovarian cancer." (PMID 31668012, 2020). "Other BCL3 transcriptional targets include PD-L1 (Programmed Cell Death 1 Ligand 1) and CAII (Carbonic Anhydrase II) that mediate cell proliferation and resistance to alkylating agents in ovarian cancer and gliomas, respectively." (PMID 34422669, 2021).
melanoma (15 papers, 2011 to 2024). A malignant, usually aggressive tumor composed of atypical, neoplastic melanocytes. "Initially, we investigated the survival curve of melanoma patients with metastasis stratified by the Bcl-3 expression level and found that the reduced survival rate of melanoma patients with metastases correlated with high levels of Bcl-3 expression." (PMID 38238702, 2024). "46% and 16% of Pecam1+ ECs were positive for both Pim3 and Bcl3 or Pim3 and Inhbb, respectively, indicating tumor-induced upregulation of the rCaps 6 h after melanoma injection." (PMID 39627185, 2024). "Analysis of Bcl-3 expression levels in nine human melanoma cell lines showed high levels of Bcl-3 expression in all except Mel Juso cells." (PMID 38238702, 2024). "The benefits of using Bcl-3 blocking instead of recently approved CDK4/6 inhibitors are that targeting Bcl-3 will only affect metastatic melanoma cells, while CDK4/6 inhibitors affect all actively dividing cells." (PMID 38238702, 2024). "The use of A27 not only hindered cell proliferation, migration, and invasion but also led to a reduction in tumor growth in animal models in vivo (An optimized Bcl-3 inhibitor for melanoma treatment, Saamarthy et." (PMID 39327470, 2024). "A small-molecule inhibitor against pirin inhibited the interaction between pirin and Bcl-3 in melanoma, leading to inhibition of melanoma cell migration." (PMID 38238702, 2024). "Earlier studies including research from our laboratory have shown that the growth and metastasis of melanoma cells are regulated by elevated expression of oncogene B-cell CLL/lymphoma 3 (Bcl-3)." (PMID 38238702, 2024). "In experimental animal models of melanoma, it was demonstrated that the use of a Bcl-3 inhibitor can influence the survival of melanoma cells." (PMID 38238702, 2024). "After establishing that BCL3ANT interferes with the expression of cyclin D1, we wanted to examine the effect of Bcl-3 inhibition in melanoma cells." (PMID 38238702, 2024). "Interrupting the interaction between Pirin and BCL3 with a Pirin inhibitor has been shown to inhibit melanoma cell metastasis via suppression of snail homolog 2 (SNAI2)." (PMID 38033031, 2023). "Pirin is a transcriptional coactivator whose influence on NF-κB dependent transcription via interaction with BCL3 was shown in the case of SNAI2 expression in melanoma cells." (PMID 24390086, 2014). "We have reported earlier that CYLD by retaining Bcl-3 in the cytoplasm reduces the expression of cyclin-D1 and consequently decreases the proliferation of keratinocytes and melanoma cells." (PMID 21573132, 2011). "High-throughput screening and in vitro experiments identified BCL3ANT as a lead molecule that could interfere with Bcl-3-mediated cyclin D1 expression and cell proliferation and migration in melanoma." (PMID 38238702, 2024). "In the present study, we focused on melanoma as a proof of concept and identified a lead molecule that could interfere with Bcl-3-mediated cyclin D1 expression as well as proliferation and migration in melanoma cells." (PMID 38238702, 2024). "Additionally, BCL3ANT reduced cyclin D1 luciferase activity in Bcl-3-overexpressing melanoma cells in a concentration-dependent manner." (PMID 38238702, 2024). "Interestingly, Inhbb and Bcl3 showed low expression in the control lungs, while Pim3, Inhbb and Bcl3 were enriched in the metastatic lungs, especially in the vicinity of melanoma cells when compared to regions distant to melanoma cells." (PMID 39627185, 2024). "Previously, we developed a second-generation Bcl-3 inhibitor that could directly interfere with Bcl-3 signaling pathway, resulting in reduced melanoma cell proliferation, invasion, and migration." (PMID 39327470, 2024). "Furthermore, in melanoma Bcl-3 promotes the migration and invasion of these cells through upregulation of Snail and Slug proteins, which play a critical role in the epithelial to mesenchymal (EMT) process." (PMID 38238702, 2024).
melanoma (continued). "Previously, Bcl-3 expression was shown to affect the cell migration and invasion of melanoma cells." (PMID 38238702, 2024). "Previously, our research group has developed a small molecule inhibitor against Bcl-3 that could directly interfere with Bcl-3-mediated cyclin D1 activity in melanoma resulting in decreased cell proliferation, cell migration, and invasion, as well as decreased tumor growth in vivo." (PMID 39327470, 2024). "A previous report showed that, in melanoma, NQO1 mediates activation of the NF-κB component p50 through stabilization of BCL3-induced cell cycle progression and proliferation." (PMID 36793872, 2023). "It has been shown that pirin-BCL3 interaction is important for the regulation of SNAI2 expression and that the inhibition of this interaction resulted in the decreased migration of melanoma cells." (PMID 24390086, 2014). "Since there are no other inhibitors against Bcl-3 in the clinical pipeline for cancer treatment, this presents a unique opportunity to develop a highly specific drug against malignant melanoma to meet an urgent clinical need." (PMID 38238702, 2024). "However, there is an interaction between Pirin, B-cell lymphoma 3-encoded protein (BCL-3), and Slug in melanoma cells, whereas in cervical cancer cells Pirin induces EMT by decreasing E-cadherin expression independent of BCL-3-Slug signaling." (PMID 33557375, 2021).
hepatocellular carcinoma (14 papers, 2009 to 2025). A malignant tumor that arises from hepatocytes. "The clinical utility of BCL-3 as a marker of prognosis is highlighted by a growing number of clinical studies: increased protein and mRNA expression has been associated with adverse clinicopathological characteristics in hepatocellular carcinoma patients." (PMID 31930327, 2020). "BCL3 expression is elevated in various hematopoietic and solid cancers, including breast and hepatocellular carcinomas." (PMID 38033031, 2023). "In hepatocellular carcinomas, BCL-3 is frequently overexpressed in tumour tissue compared with normal tissue, in conjunction with p50 and p52 NF-κB subunits." (PMID 31930327, 2020). "Expression of FOS was enhanced in human omental microvascular endothelial cells when incubated with TNF-α for 10 min, whereas BCL3, a nuclear protein primarily found in B lymphocytes, increased when human hepatocellular carcinoma cell lines (HepG2) were stimulated with TNF-α." (PMID 19925655, 2009). "Additionally, a clinical study examined immunohistochemistry from paired normal and tumour tissue in hepatocellular carcinoma and discovered BCL-3 expression resulted in advanced Tumour, Node, Metastasis stage; this was shown to have contributed to the poorer prognosis observed in these patients." (PMID 31930327, 2020). "Bcl-3 has been shown to be widely expressed in different cancer types including hepatocellular carcinoma (HCC)." (PMID 28915576, 2017). "In a mouse hepatocellular carcinoma (HCC) experiment, the expression of Bcl3, an important factor in the NF-κB pathway in senescent hepatocytes, was increased." (PMID 39781471, 2025). "Additionally, Bcl3 may be a novel therapeutic target in hepatocellular carcinoma." (PMID 35351855, 2022). "Bcl-3 has been shown to be important for Sox2 expression in murine embryonal stem cells and AKT was found to drive Sox2 expression in hepatocellular carcinoma cells." (PMID 33228022, 2020). "In Multiple Myeloma (MM), but not hepatocellular carcinoma, ChIP and Luciferase gene reporter assays demonstrated IL-6 to regulate BCL3 expression via the binding of STAT3 to the HS4 BCL3 gene enhancer." (PMID 38195591, 2024).
leukemia (14 papers, 2013 to 2024). A malignant (clonal) hematologic disorder, involving hematopoietic stem cells and characterized by the presence of primitive or atypical myeloid or lymphoid cells in the bone marrow and the blood. "BCL3 gene encodes for a transcription co-activator, previously known as B-Cell Lymphoma 3-Encoded Protein, due to its role in lymphoma and leukemia." (PMID 34946971, 2021). "This enhancer also has interactions with the promoter of GALNT5 and appears to be bound by a number of factors in K562 including GATA2, PML, TAL1 and BCL3, all of which have been implicated in the leukemia or other forms of cancer." (PMID 26576536, 2015). "In the present study, we investigated the effect of Bcl-3 antagonist A27 on B-cell lymphoma and leukemia." (PMID 39327470, 2024). "The present study aimed to investigate the effect of a Bcl-3 inhibitor on B-cell lymphoma and leukemia cells." (PMID 39327470, 2024). "BCL3 has been previously identified as a transcriptional activator in leukaemias and has recently been shown to activate an array of pathways including WNT and NFKB47." (PMID 35396535, 2022). "In leukemia cells, BCL3 has been demonstrated to up-regulate myc genes and lead to the formation of aggressive B-cell leukemia." (PMID 35399006, 2022). "How exactly BCL3 exerts its oncogenic role in leukemia and lymphoma is unclear, but it has been proposed that BCL3 can promote cell proliferation and survival by transactivating a number of different target genes." (PMID 29587428, 2018). "For example, TGF-β1, BCL3 and BRD4, which all have been linked with leukemia development were overlooked by the RD protocol." (PMID 28818039, 2017). "Since the discovery that Bcl-3 is an oncogene involved in leukemia, other studies have demonstrated the oncogenic function of Bcl-3 in solid tumors originating from breast, liver, prostate, colon, cylindromatosis, basal cell carcinoma, squamous cell carcinoma, and nasopharyngeal carcinoma." (PMID 38238702, 2024). "Pinometostat treatment alters the expression of some genes involved in leukemia control such as MicroRNA let-7B (let-7b) and RUBICON that are up-regulated, or BCL3 that is down-regulated." (PMID 31727944, 2019). "Together, we show here that treatment of human epithelial cells with pinometostat modifies the expression of few cellular genes, being an important number of them involved in the modulation of leukemia altered pathways, such as the microRNA let-7b, RUBICON, or BCL3 genes." (PMID 31727944, 2019).